ACE (angiotensin I converting enzyme)
Diseases named in the same sentence as ACE in open-access papers (continued):
Sharing a sentence is not in itself a finding about the gene and the disease.
colon carcinoma (13 papers, 2011 to 2026). "We found some evidence that the effect of ACE inhibition was stronger in colon cancer than rectum, (1.12, 1.05, 1.19; 2x10-4 and 1.04; 0.98, 1.10; 0.213, respectively) (pdiff=0.071))." (PMID 41085561, 2026). "It has also been reported to inhibit angiotensin I-converting enzyme (ACE), which results in antihypertensive activity, induces apoptosis, and arrests the G2/M phase of the cell cycle in HT-29 colon cancer and human monocytic leukemia cells (U937)." (PMID 39684444, 2024). "Then the results in vivo studies indicated that ACE inhibited solid tumours, liver and spleen metastases of colon cancer while simultaneously reducing pathological tissue damage." (PMID 34531745, 2021). "Our present study showed that ACE treatment significantly attenuated intestinal microbial dysbiosis in colon cancer-bearing mice." (PMID 34531745, 2021). "Therefore, ACE was able to modulate the abundances of intestinal flora members and regulate the intestinal flora structure in colon cancer model mice." (PMID 34531745, 2021). "We hypothesized that ACE-induced alterations in the gut microbiota inhibit the development and metastasis of colon cancer through certain pathways." (PMID 34531745, 2021). "We also examined the protein and mRNA expression levels of the anti-colon cancer action pathway, SDF-1/CXCR4 axis before and after intervention with the ACE drug pair." (PMID 34531745, 2021). "Interestingly, it was reported that the angiotensin activation ability in CT26 mouse colon cancer cells was dependent mainly on the renin-chymase pathway, rather than the renin-ACE pathway." (PMID 37175975, 2023).
liver cirrhosis (13 papers, 2010 to 2025). "From fecal 16S rRNA sequencing, we first analyzed the gut microbiota profile in different groups and found that the α diversity of the gut microbiota, including the ACE and Chao1 index, was significantly reduced in patients with liver cirrhosis (LC) compared with healthy controls (HCs) (p<0.05)." (PMID 37483387, 2023).
lymphopenia (13 papers, 2014 to 2025). Reduction in the number of lymphocytes. "High-resolution computed tomography (HRCT) and positron emission tomography with 2-deoxy-2-fluoro-D-glucose (18F-FDG PET/CT) improve systemic assessment, while soluble interleukin-2 receptor (sIL-2R), angiotensin-converting enzyme (ACE), and lymphopenia support diagnostic accuracy." (PMID 41971214, 2025). "Moreover, an increased soluble interleukin-2 receptor (sIL-2R) expression (76.2%), elevated angiotensin-converting enzyme (ACE) levels (34.8%), and lymphocytopenia (35.1%) were valuable laboratory findings." (PMID 35011651, 2021). "Our results confirm that lymphopenia is most frequently present in patients with systemic involvement and that other biological markers such as serum calcium, CRP, ACE, and the lumbar puncture analysis are non‐specific." (PMID 39279263, 2024).
ocular sarcoidosis (13 papers, 2010 to 2025). A leading cause of inflammatory eye disease is sarcoidosis. "The combination of elevated ACE and a positive 67GA scan increased the diagnostic specificity to 100% without affecting sensitivity (73%) in patients with suspected ocular sarcoidosis and normal chest radiographs." (PMID 37721575, 2023). "A combination of serum ACE level and whole-body gallium scan increases the diagnostic specificity without affecting sensitivity in patients with clinically suspicious ocular sarcoidosis who have normal or equivocal chest radiographs." (PMID 20029143, 2010). "The mean soluble IL-2 receptor (sIL-2R) level and angiotensin-converting enzyme (ACE) level were significantly higher in diagnosed ocular sarcoidosis patients compared to patients with suspected ocular sarcoidosis." (PMID 36142662, 2022). "Thirty-one of the 37 patients (83%) with proven and/or suspected ocular sarcoidosis were found to have a high level of lysozyme, while this was the case for ACE in only 11 of the 37 patients (29.7%)." (PMID 33805490, 2021). "On the other hand, serum lysozyme seems more often elevated compared to ACE in our ocular sarcoidosis cases." (PMID 33805490, 2021). "In another study considering the predictive value of serum ACE and lysozyme levels in diagnosis of ocular sarcoidosis, the sensitivity of increased serum ACE level was found as 84 %, specificity was 95 %, and predictivity was 47 %." (PMID 26879979, 2016). "The serum levels of ACE and lysozyme have been reported increased in 40 and 42 % of patients with biopsy-proven ocular sarcoidosis respectively." (PMID 26879979, 2016). "Serum levels of CXCL9 and CXCL10 have been correlated with serum ACE levels in presumed ocular sarcoidosis." (PMID 26879979, 2016). "Our main outcome parameters were the specificity and sensitivity of sIL2R, CxR and ACE in screening for ocular sarcoidosis." (PMID 26799486, 2016). "Lysozyme was found to be much more useful than ACE as a laboratory test to support the diagnosis of ocular sarcoidosis in a study performed by Papasavvas because the number of patients with normal ACE and elevated lysozyme levels were much greater in his study." (PMID 38787250, 2024). "Serum ACE and lysozyme are well documented as ocular sarcoidosis biomarkers." (PMID 37721575, 2023). "In addition, we found that lysozyme was much more sensitive than ACE in the diagnosis of ocular sarcoidosis reaching 83.7% versus 27% for ACE." (PMID 33805490, 2021). "The aim was to evaluate the usefulness of serum ACE, serum lysozyme and polyclonal antibody activation and compare the frequency of increased serum levels of lysozyme and ACE and their sensitivities and specificities in proven ocular sarcoidosis or in suspected ocular sarcoidosis cases." (PMID 33805490, 2021). "In diagnosed or suspected ocular sarcoidosis, serum levels of both CXCL9 and CXCL10 were markedly elevated and correlated with ocular disease activity and ACE level." (PMID 37721575, 2023). "It is difficult to confirm the diagnosis in patients suspected to have ocular sarcoidosis without biopsy findings or significant extraocular manifestations, such as bilateral hilar lymphadenopathy, increased serum angiotensin-converting enzyme (ACE) level, and other laboratory findings." (PMID 29785303, 2018).
ovarian carcinoma (13 papers, 2006 to 2024). A malignant neoplasm originating from the surface ovarian epithelium. "Post-diagnostic ACE-inhibitor users had a reduced ovarian cancer-specific death risk (HR 0.55, 95% CI: 0.36–0.83), the results also showed better ovarian cancer survival in higher dose users (HR 0.46, 95% CI: 0.28–0.77, p for trend 0.002)." (PMID 38439058, 2024). "We found, that using ACE inhibitors following the ovarian cancer diagnosis is associated with improved cancer-specific survival in ovarian cancer patients." (PMID 38439058, 2024). "Our result that ACE inhibitors use after ovarian cancer diagnosis is associated with reduced cancer-specific mortality risk is in agreement with results of previous studies." (PMID 38439058, 2024). "In recent meta-analyses it was concluded, that there is insufficient evidence regarding the association between ACE inhibitors or BBs and ovarian cancer survival." (PMID 38439058, 2024). "The analyses confirmed previous results showing that users of ACE inhibitors had a statistically significantly decreased risk of ovarian cancer-specific mortality." (PMID 38439058, 2024). "The risk of death due to ovarian cancer was related to the amount of ACE inhibitors consumed during the first year after diagnosis and the effect was stronger in patients, having used ACE inhibitors prior to diagnosis." (PMID 38439058, 2024). "This study demonstrated an association between ACE inhibitors and around 45% reduced risk of ovarian cancer mortality." (PMID 38439058, 2024). "The association between ACE-inhibitor use and ovarian cancer survival should be clarified in the future." (PMID 33925829, 2021). "Furthermore, our result of an association between the post-diagnostic ACE inhibitor use and lower ovarian cancer mortality is consistent with previously reported data, adjusted for BMI, smoking and other potentially confounding variables." (PMID 38439058, 2024). "When analyses were restricted to women > 50 years old at diagnosis, inverse association between ACE inhibitor use and ovarian cancer mortality remained, whereas the risk estimates for associations between BBs or CCBs use and ovarian cancer mortality were attenuated." (PMID 38439058, 2024). "Our findings imply that post-diagnosis use of ACE inhibitors may be associated with reduced ovarian cancer-specific mortality; however, further research is needed for the comprehensive assessment." (PMID 38439058, 2024). "A recent study has demonstrated serum angiotensin-converting enzyme (ACE) levels to be significantly higher in epithelial ovarian cancer (EOC) patients than in a control group." (PMID 30845964, 2019). "Because ovarian cancer cells invade surrounding tissues through the peritoneal cavity, understanding the role of angiotensin II and ACE during metastasis will be essential to assess how AGTR1 regulates cancer progression." (PMID 28439256, 2017). "Serum levels of angiotensin II converting enzyme (ACE), the key enzyme responsible for production of angiotensin II, were shown to be significantly increased in ovarian cancer patients." (PMID 28439256, 2017). "The association became stronger among ACE inhibitors users aged 51–65 years with stage I-III ovarian cancer (HR 0.26, 95% CI: 0.09–0.76, data not shown)." (PMID 38439058, 2024). "Our findings imply that treatment of cardiovascular conditions with ACE inhibitors may have an impact on survival in ovarian cancer patients; however, further studies in larger cohorts and randomised trials are needed to confirm this result." (PMID 38439058, 2024). "Moreover, in a study of women 66 + years of age with ovarian cancer, lower cancer-specific mortality was shown in patients who received ACE inhibitors or diuretics during the year following a cancer diagnosis." (PMID 38439058, 2024).
ovarian carcinoma (continued). "Namely, in women with serous cancers CCB and ACE inhibitor use was associated with a significantly decreased ovarian cancer death risk, but no such association was observed in “Other” histological type category." (PMID 38439058, 2024). "The risk of ovarian cancer death was reduced in angiotensin-converting enzyme inhibitors (ACE inhibitors) users vs. non-users (HR 0.55, 95% CI: 0.36–0.83)." (PMID 38439058, 2024). "Increased serum ACE levels have been detected in epithelial ovarian cancer patients." (PMID 35565312, 2022). "ACE levels were significantly upregulated in patients with ovarian cancer." (PMID 27660742, 2016). "A number of large cohort studies on the association between the antihypertensive medication use and ovarian cancer death risk showed a significant beneficial effect of post-diagnostic angiotensin-converting enzyme inhibitors (ACE inhibitors) use on cancer-specific survival compared to not users." (PMID 38439058, 2024). "The level of serum angiotensin-converting enzyme (ACE), which is responsible for cleaves of two amino acids from Ang I to form angiotensin II, is significantly higher in epithelial ovarian cancer (EOC) patients than in a control group." (PMID 35008474, 2021). "Furthermore, we found that ACE, an enzyme producing angiotensin II in the RAS, was expressed in the tumour stroma of ovarian cancer (data not shown)." (PMID 16434990, 2006).
pulmonary edema (13 papers, 2020 to 2025). Accumulation of fluid in the lung tissues causing disturbance of the gas exchange that may lead to respiratory failure. "For example, the ACE D allele increases the level of ACE-1 but decreases that of ACE-2, leading to an increase in angiotensin-2 and pulmonary edema progression, by increasing microvascular permeability." (PMID 38058963, 2023). "Scorpion venom inhibits angiotensin converting enzyme (ACE), resulting in accumulation of bradykinin, which is implicated in the development of pulmonary edema." (PMID 32899951, 2020). "Among the cats with pulmonary oedema, seven received furosemide and two received angiotensin-converting enzyme (ACE) inhibitors before blood was collected." (PMID 40999563, 2025). "For instance, the ACE D allele causes an increase in ACE-1 level and a decrease in ACE-2 level, causing an increased level of angiotensin-2 and progression of pulmonary edema, through increased microvascular permeability." (PMID 34603503, 2021). "Angiotensin II induces pulmonary oedema in rabbits, while in a rat model of smoke inhalation-induced ARDS, inflammation pulmonary oedema and histological changes were possibly attributed to abnormal expression of ACE and ACE2 related pathway." (PMID 33233715, 2020).
resistant hypertension (13 papers, 2009 to 2026). "In the resistant hypertension group, the most commonly used anti-hypertensive drug was β-blockers (71.7%) followed by ACE inhibitors (69.8%) and CCBs (54.7%)." (PMID 24053215, 2013). "Genetic variation in genes coding for enzymes metabolising antihypertensive drugs, may affect the efficacy of angiotensin converting enzyme (ACE) inhibitors such as enalapril, potentially leading to resistant hypertension (RHTN)." (PMID 40534840, 2025).
thrombophilia (13 papers, 2015 to 2025). A condition characterized by an abnormally high level of thrombi. "Likewise, the women from our study diagnosed with mixed thrombophilia tested positive in 3.95% of the cases for the homozygote form of ACE_insertion_deletion mutation (angiotensin converting enzyme gene), which was demonstrated to increase miscarriage risk in European women." (PMID 37241083, 2023). "This review explores the interlinking of thrombophilia, PE, and RPL pathways through the ACE gene and associated mechanisms." (PMID 36532100, 2022). "Like thrombophilia genes, the ACE gene also reduces fibrinolysis and restricts bleeding during pregnancy." (PMID 36532100, 2022). "In summary, we found that 85% of our critically ill patients had the ACE D/D, the ACE I/D genotype was found in 10%, and 100% had multiple heterozygosity and homozygosity for factors related to inherited thrombophilia." (PMID 34441050, 2021). "Further to the functional genetic variation in SERPINE1 itself, its levels are positively mediated by ACE, through its active proteolytic product angII, which triggers PAI-1 secretion, therefore inhibiting fibrinolysis and resulting in hypercoagulability." (PMID 41155403, 2025).
aortic stenosis (12 papers, 2015 to 2026). Aortic valve stenosis is a aortic valve disease caused by the incomplete opening of the aortic valve. "The majority of the patients were lacking the golden drug in management: beta-blockers in mitral stenosis, ACE inhibitors or ARBs in mitral and aortic regurgitation, and digoxin, antiplatelets, and statins in aortic stenosis." (PMID 37181974, 2023). "They used single nuclei RNA sequencing and analyzed the expression of ACE and ACE2 in the single-cell levels in the human heart with aortic stenosis (AS), HF with reduced ejection fraction (HFrEF), and healthy donor hearts." (PMID 33228225, 2020). "Other pharmacological approaches, such as statins, ACE inhibitors, PCSK9 inhibitors, or DPP-4, have not demonstrated many benefits in aortic stenosis outcomes." (PMID 40870420, 2025).
melanoma (12 papers, 2016 to 2025). A malignant, usually aggressive tumor composed of atypical, neoplastic melanocytes. "In addition, we found that stimulation of ACE by Ang-II caused the melanoma cells to migrate, at least in part due to decreased vinculin expression, a focal adhesion structural protein." (PMID 27992423, 2016). "Two patients (numbers 10 and 12) were classified as “probable DISR” despite concurrent melanoma metastases, based on the typical radiological presentation, elevated sIL2R/ACE levels, and/or regression of symptoms and lesions under systemic steroid therapy." (PMID 40887791, 2025). "ACE overexpression results in reduced tumour growth in a B16 melanoma murine model, but when ACE activity was inhibited or knocked out, tumour size reverted back to wild-type proportions." (PMID 36016727, 2022). "Summing up, our data indicate that ACE possesses the best activity toward the A2058 melanoma cells; thus, it was chosen for further investigations." (PMID 36010420, 2022). "Contrarily, all the AC extracts affected the 3T3-L1 cells’ viability to a much lesser extent, and as an example, the ACE activity against the A2058 melanoma cells was almost 5 × 10−3 superior to that exerted against the 3T3-L1 cells." (PMID 36010420, 2022). "Animal models with ACE overexpression in immune cells have shown remarkable resistance to immunological challenge, including B16 melanoma." (PMID 36016727, 2022). "Prophylactic vaccination with DCs pulsed with lysates of TECs (positive for angiotensin-converting enzyme (ACE) activity) isolated from the lung with metastases was shown to significantly suppress lung metastasis in the B16/BL6 mouse melanoma model." (PMID 32264958, 2020). "We further show that ACE is involved in TM-5 cell migration, another aspect of melanoma carcinogenesis." (PMID 27992423, 2016). "More recently, ACE was shown to act as a receptor for Ang-II, and its expression level was demonstrated to be higher in melanoma cells compared to their normal counterparts." (PMID 27992423, 2016). "In the current study, we investigated novel roles of ACE as Ang-II receptor, demonstrating that ACE regulates cell proliferation and migration in melanoma cells." (PMID 27992423, 2016). "ACE activation regulates melanoma cell proliferation and migration." (PMID 27992423, 2016). "However, more clinical studies are still needed in order to justify the usage of ACE inhibitors or AT1 blockers for treating melanoma and other malignancies." (PMID 27992423, 2016). "Further studies in melanoma cells (TM-5) showed that Ang-II induced cell proliferation through ACE activation, an event that could be inhibited either by ACE inhibitor (Lisinopril) or by the silencing of ACE." (PMID 27992423, 2016). "Recent analysis of mice overexpressing ACE in monocytes, macrophages, and other myelomonocytic cells shows that these animals have a marked increase in resistance to experimental melanoma and to infection byListeria monocytogenes or methicillin-resistantStaphylococcus aureus (MRSA)." (PMID 27018193, 2016). "Taken together, our findings here suggest a novel function of ACE in the pathology of melanoma and open new paths to further studies, where ACE, as a receptor, might function as a possible therapeutic target aiming to avoid the progression of the disease." (PMID 27992423, 2016). "Even though murine macrophages (in contrast to human macrophages) express only low levels of ACE, studies with transgenic mice genetically engineered to express high levels of the enzyme in macrophages, revealed an exaggerated inflammatory response that can limit melanoma growth." (PMID 31042763, 2019). "Previous studies have demonstrated an association of the use of ACE inhibitors and angiotensin II receptor 1 blockers with reduced risk of development of skin SCC, and β-blockers administration which reduce renin levels, is associated with improved survival of patients with malignant melanoma." (PMID 28634582, 2017).